RNF169 (ring finger protein 169)
Description:
Probable E3 ubiquitin-protein ligase that acts as a regulator of double-strand breaks (DSBs) repair following DNA damage. Functions in a non-canonical fashion to harness RNF168-mediated protein recruitment to DSB-containing chromatin, thereby contributing to regulation of DSB repair pathway utilization. Once recruited to DSB repair sites by recognizing and binding ubiquitin catalyzed by RNF168, competes with TP53BP1 and BRCA1 for association with RNF168-modified chromatin, thereby favouring homologous recombination repair (HRR) and single-strand annealing (SSA) instead of non-homologous end joining (NHEJ) mediated by TP53BP1. E3 ubiquitin-protein ligase activity is not required for regulation of DSBs repair.
Synonyms: KIAA1991
Tractability: PROTAC: UniProt records ubiquitination sites on it; ubiquitination databases record sites on it; its protein half-life has been measured.
Gene: Protein-coding gene on chromosome 11 (74,748,849 to 74,842,413, forward strand). Ensembl gene ENSG00000166439.
Subcellular location: Chromosome; Nucleus, nucleoplasm
Subcellular location (Human Protein Atlas): Nuclear bodies; Nucleoplasm; Cytosol; Nucleoli; Nucleoli rim
Gene Ontology:
Molecular function: K63-linked polyubiquitin modification-dependent protein binding; nucleosome binding; protein binding; ubiquitin-modified histone reader activity; ubiquitin-protein transferase activity; ubiquitin protein ligase activity
Biological process: DNA damage response; double-strand break repair via homologous recombination; negative regulation of double-strand break repair; double-strand break repair; chromatin organization; protein ubiquitination
Cellular component: chromosome; cytosol; nuclear body; nucleolus; nucleoplasm; nucleus; site of double-strand break
Genetic constraint (gnomAD): Loss-of-function variants: 24 observed, 43.44 expected, observed/expected ratio (o/e) 0.55, 90% interval 0.4 to 0.78. The upper end of that interval is the gene's LOEUF score, 0.78, which puts it in group 3 of 6, group 1 being the genes least tolerant of losing a copy. Missense variants: 837 observed, 783.92 expected, observed/expected ratio (o/e) 1.07, 90% interval 1.01 to 1.13. Synonymous variants: 372 observed, 313.27 expected, observed/expected ratio (o/e) 1.19, 90% interval 1.09 to 1.29.
Homologues: Orthologues: chimpanzee RNF169 (99% identical), macaque RNF169 (97% identical), dog RNF169 (87% identical), pig RNF169 (87% identical), guinea pig RNF169 (85% identical), rabbit RNF169 (83% identical), mouse Rnf169 (79% identical), rat Rnf169 (78% identical), tropical clawed frog RNF169 (34% identical), zebrafish rnf169 (31% identical), Caenorhabditis elegans T02C1.2 (7% identical). Paralogues in human: RNF168 (18% identical).
Diseases named in the same sentence as RNF169 in open-access papers:
RNF169 is named in the same sentence as 14 diseases in open-access papers, as found by Europe PMC text mining. Sharing a sentence is not in itself a finding about the gene and the disease. The quoted sentences say what the papers report.
pancreatic adenocarcinoma (2 papers, 2022 to 2025). "Additionally, the overexpression of RNF169 has been linked to poor prognosis in pancreatic adenocarcinoma." (PMID 40136626, 2025).
hepatocellular carcinoma (1 paper, 2024). A malignant tumor that arises from hepatocytes.
melanoma (1 paper, 2021). A malignant, usually aggressive tumor composed of atypical, neoplastic melanocytes. "One of these, E3 ubiquitin ligase RNF169 is deubiquitylated and stabilized by USP7 in response to DNA double-strand breaks, and is significantly decreased in the USP7 knockdown, which suggests USP7 in melanoma also plays a role in DNA repair." (PMID 33869052, 2021).
pancreatic cancer (1 paper, 2025). "Notably, high levels of Rnf169 expression correlate with poor prognosis in pancreatic cancer cases." (PMID 39940814, 2025).
pancreatic ductal carcinoma (1 paper, 2023). "The role of RNF169 in development and human disease has not been extensively investigated; it was suggested that that high expression of RNF169 could be a prognostic marker in pancreatic ductal carcinoma although this association has not been experimentally validated yet." (PMID 37900285, 2023).
uterine carcinosarcoma (1 paper, 2022). A usually aggressive malignant neoplasm arising from the uterine corpus and less often the cervix. "In contrast, the expression of RNF169 was significantly decreased in uterine corpus endometrial carcinoma (UCEC) and uterine carcinosarcoma (UCS) tissues compared with normal tissues." (PMID 36685833, 2022).
cancer (5 papers, 2019 to 2025). A tumor composed of atypical neoplastic, often pleomorphic cells that invade other tissues. "In correlation with the predicted cancer pathways, DYRK1B was also found to have a functional association with RNF169, which predicts its role in DNA damage." (PMID 35454940, 2022). "Next, we compared the overall survival (OS) and disease-free survival (DFS) of patients in terms of RNF169 expression levels to analyse the prognostic value of RNF169 across cancers." (PMID 36685833, 2022). "In this study, RNF169 was found to be upregulated in a variety of human carcinomas, including CHOL, LAML, LGG, STAD and PAAD, but downregulated in UCEC and UCS." (PMID 36685833, 2022).
tumours (1 paper, 2022). "Our results suggest that ncRNA-mediated RNF169 upregulation is associated with poor prognosis and tumour immune infiltration in patients with PAAD." (PMID 36685833, 2022). "To determine the clinical relevance of RNF169 in PAAD, we used the GEPIA database to analyse the correlation of RNF169 expression with different tumour stages and found that there was a significant correlation between them." (PMID 36685833, 2022). "To understand the potential role of RNF169 in carcinogenesis, we sought to investigate its expression in different human tumours." (PMID 36685833, 2022). "Based on the results above regarding cytokines, chemokines and chemokine receptors, we further analysed the correlation between RNF169 mRNA expression and immune cell infiltration in tumours." (PMID 36685833, 2022). "In addition, analysis with the TISIDB and TIMER databases revealed that RNF169 expression was positively correlated with tumour immune infiltration in PAAD." (PMID 36685833, 2022). "Our results showed that RNF169 was correlated with some tumour-infiltrating lymphocytes in PAAD." (PMID 36685833, 2022).
RNF169 also shares sentences with these, for which no sentence is quoted: acute myeloid leukemia (1 paper); atherosclerosis (1); autoimmune thyroid disease (1); cholangiocarcinoma (1); inflammatory bowel disease (1); uterine corpus endometrial carcinoma (1).